BRAF (B-Raf proto-oncogene, serine/threonine kinase)
Diseases named in the same sentence as BRAF in open-access papers (continued):
Sharing a sentence is not in itself a finding about the gene and the disease.
melanoma (continued). "Median OS was 7.5 months for concomitant CTLA-4-inhibitors, 17.8 months for concomitant BRAF-inhibitors and 20.4 months for concomitant anti-PD-1 treatment in a retrospective study of 108 melanoma patients receiving SRT for brain metastases (notably, 40% of patients received an additional WBRT)." (PMID 32487100, 2020). "Gain-of-function of V-Raf Murine Sarcoma Viral Oncogene Homolog B (BRAF) is one of the most frequent oncogenic mutations in numerous cancers, including thyroid papillary carcinoma, melanoma, colon, and lung carcinomas, and to a lesser extent, ovarian and glioblastoma multiforme." (PMID 33260892, 2020). "HDAC inhibitors were shown to sensitize melanoma cells to BRAF/MEK inhibitors." (PMID 32266211, 2020). "We then postulated that a low expression of BRAF gene may translate in a lower responsiveness of melanoma cell lines to BRAF specific inhibitors." (PMID 32393282, 2020). "A recent study not only identified a novel epigenetic mechanism of drug resistance in BRAF V600E mediated melanoma, but also utilized this information for developing combinatorial therapies that could overcome drug induced resistance." (PMID 32046099, 2020). "For example, whether the susceptibility of SCD1, as revealed in the mesenchymal M381 cells, applies more generally across mesenchymal BRAF mutant melanoma tumors, is both intriguing and important, given the challenges in drugging such tumors." (PMID 32973134, 2020). "These patients do not, however, have increased risk of classic BRAF-mutated melanoma, although ~ 75% of the cardiofaciocutaneous syndromes result from germline BRAF mutations, and pigmented nevi are very distinct in this syndrome and help to define it." (PMID 32066498, 2020). "The success of BRAF inhibitors in melanoma led to similar studies in NSCLC." (PMID 33276639, 2020). "BRAF mutation was well-reported in papillary thyroid cancer, colorectal cancer, and melanoma, but not NSCLC in Chinese population due to its low prevalence." (PMID 32411601, 2020). "Radiation upregulated B7-H3 expression on human M21-R melanoma cells, resistant to BRAF inhibitors." (PMID 32894202, 2020). "Given the upregulation of Gal‐1 following BRAF inhibition in melanoma cell lines, we hypothesized that increased expression/secretion of Gal‐1 would facilitate the deletion of tumor‐interacting T cells." (PMID 32330348, 2020). "Indeed, in the past few years, clinical treatment of BRAF-mutant melanoma patients shifted toward a vertical combination of BRAF and MEK inhibitors, able to determine major improvements in terms of OS and PFS." (PMID 33036192, 2020). "PREX2 truncation E824∗ was found to cooperate with NRAS mutations but not with BRAF V600E mutation, to accelerate melanoma development." (PMID 32850962, 2020). "Of note, coexistence of BRAF V600E mutation and EZH2 amplification is rather prevalent in melanoma." (PMID 32850962, 2020). "By contrast, the V600 BRAF mutation, a mutation common in human melanoma, was not identified in the melanoma B16F10 model." (PMID 31898484, 2020). "These indicate that the transient differentiation towards a more melanocytic state may be a general early-acting mechanism that melanoma cells utilize in response to BRAF inhibition, in spite of their initial cell states." (PMID 32393797, 2020). "First, we tested whether BRAF and MEK inhibitors, which are commonly used treatment modalities for BRAF mutant melanoma patients, show differential killing of parental versus TR cells." (PMID 32770055, 2020). "Interestingly, a subset of resistant BRAF mutant melanoma cells shows enrichment in the signatures related to inflammation and nuclear factor-kappa B (NF-κB) signaling." (PMID 32466585, 2020). "Hence, we chose the A375 and C32 melanoma cell lines as a model to investigate the potential inhibition of BRAF-related molecular phenomena." (PMID 32610527, 2020).
melanoma (continued). "HI-511, a novel dual-target inhibitor against both AURKB and BRAF V600E, could achieve durable suppression of melanoma growth, even drug-resistant melanoma growth." (PMID 32863956, 2020). "We demonstrate the performance of the method in the context of BRAF-V600E melanoma treatment, where the optimal solutions predicted a number of co-inhibition partners for vemurafenib, a selective BRAF-V600E inhibitor, approved for advanced melanoma." (PMID 33370253, 2020). "BRAF-mutant melanoma patients respond to BRAF inhibitors and MEK inhibitors (BRAFi/MEKi), but drug-tolerant cells persist, which may seed disease progression." (PMID 31932756, 2020). "BRAF+ melanomas are correlated with SSM subtype, and the presence of mitoses." (PMID 32637031, 2020). "Thus, the detection rate of ctDNA and the value of ctDNA-based longitudinal monitoring in non-BRAF melanoma patients need to be specifically assessed." (PMID 33339135, 2020). "Here, we analyzed data from the cutaneous melanoma The Cancer Genome Atlas Network (TCGA) transcriptomic and proteomic databases for differential expression of apoptosis molecules between melanomas with or without BRAF hotspot mutations." (PMID 32764384, 2020). "Vemurafenib was approved for the treatment of BRAF-mutant melanoma in 2011." (PMID 32523649, 2020). "Interestingly, higher concentrations of SB590885 also negatively affected the growth of NRAS-mutated cell lines, indicating the possibility of additional, BRAF-independent, cytotoxic activity of the pyridinyl imidazole compounds in melanoma cells." (PMID 32531927, 2020). "Interestingly, as opposed to some EGFR mutant lung cancer, CPIs seem to work fairly well in BRAF-mutant melanoma." (PMID 32258034, 2020). "Taken together, we have identified a compound that is effective in inducing apoptosis in both BRAFV600E and BRAF WT melanoma and has the potential to be readily translated to the clinic especially in the case of BRAF WT melanoma where fewer approved treatment options exist." (PMID 32085796, 2020). "Mainly, the miR-17 family was linked to melanoma progression and individuated in non-responders or patients expressing high levels of PD-L1 and resistance to BRAF/ MEK inhibitors." (PMID 32645881, 2020). "However, at lower E:T ratio, CAR T cells demonstrate more potent in vitro antitumor activity with irradiated BRAF inhibitor resistant melanoma cells." (PMID 32894202, 2020). "A paradigmatic example is the development of resistance to MAPKi in BRAF-mutant melanomas." (PMID 33202944, 2020). "Also, in melanoma cells macrophages conferred resistance to BRAF inhibitors in mouse and human tumor models, which was overcome by blocking the MAPK pathway or VEGF signaling." (PMID 32656079, 2020). "In addition, JNK pathway inhibition sensitized BRAF mutant melanoma cells to genetically modified vaccinia virus-mediated cell death." (PMID 32252279, 2020). "The predominant mutation of BRAF prompted the development of the BRAF inhibitors vemurafenib and dabrafenib, which were FDA approved as mono-therapeutic agents in BRAFV600E-mutant melanoma." (PMID 33255177, 2020). "Rare BRAF mutations (V600 non-E/K and non-V600) account for 5% of BRAF-mutated melanoma, and their role in tumorigenesis and response to target therapy is still to be elucidated." (PMID 33233603, 2020). "As ALK fusions have recently been shown to be involved in resistance to BRAF inhibitors in melanoma, combinatorial therapies combining ALK inhibitors with other targeted therapies might lead to some therapeutic benefit in a subset of CRC patients." (PMID 32019056, 2020). "BRAF inhibition is one of the current approaches to treat melanoma patients." (PMID 33396645, 2020). "Trametinib (Mekinist) is a selective MEK1/2 inhibitor with activity against BRAF V600 melanomas." (PMID 32352219, 2020). "A100 sensitizes dabrafenib-resistant melanoma cells to BRAF protein kinase inhibitors." (PMID 32092958, 2020).
melanoma (continued). "Interestingly, the T-type calcium channel blocker mibefradil, which was previously shown to restore the sensitivity of resistant melanoma cells to BRAF and MEK inhibitors, was also able to reduce vem-induced HER3 and STAT3 activation." (PMID 33327495, 2020). "Because melanoma patients commonly harbor genetic alterations in BRAF, NRAS, CDKN2A, or NF1 genes that contribute to tumor progression, we examined potential associations between these genetic alterations and IRAK-M levels in melanoma cell lines and patient samples." (PMID 32533049, 2020). "Unlike what occurrs in melanoma, mCRC patients with BRAF V600E mutation do not respond to BRAF inhibitors." (PMID 36046264, 2020). "The oncogenic BRAF can lead to immunomodulation and immune escape in melanoma, by i) the secretion of immunosuppressive cytokines in the microenvironment; ii) eliciting immune suppressive phenotype of the immune cells in the microenvironment; iii) modulating the MHC level in tumor cells." (PMID 32054102, 2020). "Moreover, SphK1 inhibition, using either FTY720 or SKI-I in several melanoma cell lines, increased their sensitivity to the BRAF inhibitor vemurafenib." (PMID 33121001, 2020). "Our findings that PGE2 can be suppressed in nevi (including BRAF-mutant nevi) in subjects at increased risk for melanoma suggest that PGE2 in nevi may be a useful biomarker and tissue target in future melanoma chemoprevention studies." (PMID 31906519, 2020). "Each of these variants of uncertain significance occurred in BRAF, NRAS, or NF1 mutant melanomas." (PMID 32483240, 2020). "Approval in 2011 of the BRAF-inhibitor vemurafenib and the cytotoxic T-lymphocyte-associated protein 4 (CTLA-4)-antibody ipilimumab has resulted in significant improvements in the treatment of advanced melanoma." (PMID 33007949, 2020). "To reiterate, evaluation of the activity of OXPHOS complexes showed higher levels in BRAF-mutated and BRAF/NRAS wild-type melanoma cell lines compared to HDFs, most likely due to a higher mitochondrial mass as indicated by VDAC1 immunostaining and activity of citrate synthase." (PMID 33007949, 2020). "Studies conducted in melanoma models demonstrated the ability of ABT-737 to empower the efficacy of several therapeutic strategies including immunotoxins and BRAF or MEK inhibitor in BRAF-mutated cells." (PMID 32455818, 2020). "Overall, cell line-specific expression patterns of miRNAs were apparent, reflecting the high intrinsic heterogeneity of melanoma cells, which were not influenced by presence of either the BRAF or NRAS mutations." (PMID 32183388, 2020). "The acquired resistance to BRAFi through the reactivation of the MAPK pathway, occurring upstream, downstream or at the BRAF level, plays a crucial role in the majority of patients affected by advanced melanoma due to the relatively short PFS observed when treated with BRAFi alone." (PMID 33419275, 2020). "Our data indicate this combination induced cell death in a broad range of melanoma cell lines, including melanoma initiating cell populations, and was more potent in melanoma cells without BRAF-V600E/K mutations." (PMID 32764384, 2020). "Cyclin D1 amplification (CCND1) is observed in about 15–20% of all BRAF-mutant melanoma." (PMID 32092958, 2020). "However, there are no clinical reports investigating the treatment effect of COX2 inhibitors on BRAF/MEKi melanoma resistance." (PMID 32967672, 2020). "For example, the ‘IL2 signaling events mediated by PI3K’ pathway (ngenes = 32) could predict the essentiality of BRAF in melanoma cell lines." (PMID 32620799, 2020). "BRAF, MEK, and Erk are important targets for treating BRAF-mutant melanoma and other cancers." (PMID 32493414, 2020). "Interestingly, the inhibition of BRAF in melanoma cell lines has been reported to achieve high levels of NAD, which were activated by the overexpression of nicotinamide phosphoribosyltransferase (NAMPT), the most important NAD biosynthetic enzyme." (PMID 32858528, 2020).
melanoma (continued). "Interestingly, their expressions were independent of the status of key melanoma mutations, including BRAF, neurofibromin 1 (NF1), and RAS mutations and triple wild type in melanoma." (PMID 33014847, 2020). "Taken together, we argue that a pharmacological intervention with RAC1 inhibitor (or its downstream effectors) in combination with anti-PD-L1/PD-1 antibody may provide a novel therapeutic opportunity in BRAF inhibitor-resistant melanoma patients." (PMID 32545340, 2020). "Notably, SREBP-1 inhibition enhances the sensitivity to BRAF inhibitors in a pre-clinical PDX model of melanoma." (PMID 31910904, 2020). "Globally, about two-thirds (184 cases) of Sardinian melanoma patients were found to carry a BRAF or NRAS mutation, even considering that some cases were not analyzed for NRAS mutations." (PMID 32751423, 2020). "Our in vitro and in vivo data showed that the simultaneous targeting of BCL2 and MCL1 is effective in treating advanced melanoma, and this combination is more potent in melanomas without the BRAF-V600E/K variant." (PMID 32764384, 2020). "Pembrolizumab can to be administered as the first line therapy (BRAF wildtype melanoma) or after treatment with ipilimumab, in a combination with anti-CTLA-4 or in patients with BRAF mutations after treatment BRAF inhibitor such as vemurafenib, sorafenib and dabrafenib." (PMID 33092131, 2020). "BRAF, NRAS and TERT mutations occur in more than 2/3 of melanomas." (PMID 33122747, 2020). "MiR-92a-1-5p is also downregulated in BRAF inhibitor-resistant melanoma cell lines and one of its targets, S100A9 could play a role in resistance to BRAF inhibitors." (PMID 32183388, 2020). "Therefore, if BRAF (v-Raf murine sarcoma viral oncogene homolog B1) inhibitors can be combined with mitochondrial function inhibitors melanoma cell proliferation can be blocked at both levels." (PMID 32509589, 2020). "Alternative drug targets such as miR-107 may provide a promising approach to improve the chemosensitivity of melanoma to BRAF inhibitors." (PMID 32169117, 2020). "Thus, in melanoma cells resistant to BRAF inhibition, phendione treatment or PP2A depletion activates the MAPK cascade and cell cycle entry concurrently with DNA damage signaling and apoptosis." (PMID 32241802, 2020). "With the developed primer in the assay being able to recognize another frequently found BRAF V600K mutation (GTG > AAG), the performance of the assay in detecting the V600K mutation was also evaluated using genomic DNA from V600K-positive melanoma cell line, LM-MEL-42 (V600K heterozygote)." (PMID 33037234, 2020). "MEK inhibitors also display some immunomodulatory activity, including in BRAF wild type melanoma." (PMID 32645969, 2020). "Indeed, a cooperation between NF1 mutations and BRAF mutations was described to overcome OIS and to affect the melanoma response to targeted therapies." (PMID 31906480, 2020). "Melanomas with BRAF class-1 (V600 mutations) respond well to current FDA-approved BRAF inhibitors (vemurafenib, dabrafenib, and encorafenib), as well as combined BRAF/MEK inhibitor therapy." (PMID 32695793, 2020). "In another report, resistance in melanoma patients was discovered following the use of the combination of the Hsp90 inhibitor XL888 with the BRAF inhibitor vemurafenib, but the use of dinaciclib as a CDK2 inhibitor abolished the resistance of patients to the combination." (PMID 32397330, 2020). "Additional evidence that CDK6, ETV5, and JUN may confer resistance to BRAF inhibition comes from our analysis of two independent melanoma cohorts." (PMID 32413516, 2020). "Trametinib (GSK1120212), cobimetinib (GDC-0973), and binimetinib (MEK162) are all potent selective inhibitors of MEK1 and MEK2 and are associated with significant cell growth inhibition in in vitro experiments and antitumor activity in mouse models of BRAF-mutant melanoma." (PMID 33036192, 2020).
melanoma (continued). "In patients, these melanomas are mostly treated with combination therapy based on the use of BRAF/MEK inhibitors, but the duration of response is variable and patients frequently experience recurrence: new treatment strategies, especially different combinations, are therefore needed." (PMID 33202906, 2020). "Rapidly progressing cases of BRAF-MT advanced melanoma may be better served with BRAF/MEK inhibition." (PMID 32545409, 2020). "In BRAF mutant melanoma and non-small cell lung cancer (NSCLC), inhibition of two components of the same oncogenic pathway (BRAF + MEK, referred to as “vertical targeting”) has been shown to provide more lasting clinical benefit compared to inhibition of only BRAF4,5." (PMID 32572029, 2020). "Although nivolumab plus ipilimumab combined therapy is one of the first-line therapies for unresectable melanoma, and is a most effective protocol for BRAF wild-type melanoma, the frequency of serious adverse events is higher than that with anti-PD1 Ab monotherapy." (PMID 32707850, 2020). "The confirmation of a crosstalk between these pathways could provide a potential target for combinatorial therapeutic strategies for BRAF-mutant melanoma either at the level of EGFR and/or PGE2 production." (PMID 31819183, 2020). "In melanoma, TPMs have been shown to associate with poor disease-free and melanoma-specific survival and if simultaneously present with BRAF/NRAS oncogenic mutations, it could predict worst disease-free progression and melanoma-specific survival." (PMID 32674474, 2020). "Similarly, HDAC8 expression was increased in malignant melanoma cell models of acquired resistance to BRAF inhibitors due to the deacetylation of the transcription factor CJUN, which promotes the subsequent upregulation of EGFR and ERK signaling." (PMID 32046099, 2020). "Here, we observed that treatment of melanoma cells with the B-Raf Proto-Oncogene, Serine/Threonine Kinase (BRAF) inhibitor vemurafenib caused an increased cell surface expression and activation of human epidermal growth factor receptor 3 (HER3) by shed ligands." (PMID 33327495, 2020). "We adopt a series of BRAF-mutant patient-derived melanoma cell lines as a model system." (PMID 32973134, 2020). "Giant congenital naevi are pigmented childhood lesions that often have NRAS mutations rather than BRAF mutations; the presence of these lesions also confers an enhanced risk of early onset melanoma." (PMID 33024276, 2020). "The aim of this work was to unveil the metabolic characteristics of acquired resistance to BRAF inhibitors in BRAF-mutant melanoma cells and identify novel pathways that could provide targeted combinatorial strategies with BRAF inhibitors." (PMID 31819183, 2020). "Melanoma cell growth is typically driven by the ERK/MAPK pathway, which is hyper‐activated in at least 80% of melanomas that occur through mutations in NRAS (~20%), BRAF (~50%) and NF1 (~14%)." (PMID 31323160, 2020). "They include: BRAF inhibitors such as vemurafenib and dabrafenib used alone or in combination with the mitogen-activated protein kinase (MEK) inhibitor like trametinib dedicated to patients with a BRAFV600 mutation (35–50% of melanoma)." (PMID 32610527, 2020). "Interestingly, an elegant study using a BRAF mutant melanoma model demonstrated that treatment with BRAF inhibitors induces drug-sensitive cells to secrete factors that promote the survival, proliferation, and metastasis of preexisting resistant clones." (PMID 33213500, 2020). "Together, our data suggest that intermittent inhibition of BET proteins may improve the duration of responses following BRAFi/MEKi treatment in BRAF-mutant melanoma." (PMID 31932756, 2020). "Furthermore, we uncovered that A20-mediated Akt activation was also implicated in rendering acquired resistance to Vemurafenib in BRAF-mutant melanoma." (PMID 32968045, 2020). "Furthermore, a subset of BRAF/MEK-inhibitor-resistant melanoma cells showed sensitivity towards different IKKε/TBK1 inhibitors." (PMID 32630674, 2020).